GLS (glutaminase)
Diseases named in the same sentence as GLS in open-access papers (continued):
Sharing a sentence is not in itself a finding about the gene and the disease.
amyotrophic lateral sclerosis (1 paper, 2013). Amyotrophic lateral sclerosis (ALS) is a neurodegenerative disease characterized by progressive muscular paralysis reflecting degeneration of motor neurons in the primary motor cortex, corticospinal tracts, brainstem and spinal cord. "Interestingly, a previous study has shown that cell lines with a known familiar mutation for amyotrophic lateral sclerosis (ALS) have the same expression pattern, with up-regulated PDK1 and down-regulated GLS, as compared to the wild-type cell line." (PMID 23936387, 2013).
aortic valve disease (1 paper, 2025). "Piezo1 activation stimulates calcium‐dependent YAP activation, modulates glutaminase (GLS1)‐mediated glutamine hydrolysis, and drives osteogenic differentiation through histone acetylation of Runt‐related transcription factor 2 promoters, ultimately leading to calcified aortic valve disease." (PMID 40066231, 2025).
aspergillosis (1 paper, 2023). Aspergillosis is an infection, growth, or allergic response caused by the Aspergillus fungus. "In an in vivo model, inhibition of glutaminase increased susceptibility to experimental aspergillosis, as revealed by the increased fungal burden and inflammatory pathology, and the defective cytokine production in the lungs." (PMID 36475892, 2023).
autoimmune hepatitis (1 paper, 2025). Hepatitis caused by autoantibodies. "In autoimmune hepatitis (AIH), GLS antagonists like JHU083 and DON not only attenuate T cell activation and reduce the Th1/Th17 ratio but also downregulate SLC7A5 mRNA expression, further dampening mTOR pathway activation." (PMID 40155378, 2025).
cardiac hypertrophy (1 paper, 2024). "Furthermore, although we did not use any glutamine treatment, glutaminase gene expression, an enzyme responsible for glutamine catabolism, was augmented in FF dams, suggesting lower protection from this amino acid against gestational fructose exposure-induced cardiac hypertrophy." (PMID 39335874, 2024).
cardiac ischemia (1 paper, 2022). "rno-miR-23 facilitates cardiac ischemia/reperfusion injury by targeting glutaminase mRNA which is involved in the synthesis of glutathione." (PMID 35677105, 2022).
cartilage tumours (1 paper, 2018). "Therefore, glutaminase is higher expressed in high-grade compared to low-grade cartilage tumours but does not correlate to IDH1/2 mutation status." (PMID 29576625, 2018).
coronary heart disease (1 paper, 2022). "The results showed that six CRGs (LIAS, LIPT1, DLAT, PDHB, MTF1, and GLS) were markedly differentially expressed between stable coronary heart disease (stable_CAD) and AMI." (PMID 36440046, 2022).
COVID-19 (1 paper, 2023). A disease caused by infection with severe acute respiratory syndrome coronavirus 2. "Considerable evidence indicates that the bioavailability of glutamine is critically depleted in COVID-19 patients, perhaps secondary to a rise in GLS activity that directs the conversion of glutamine to glutamate." (PMID 37108759, 2023). "Notably, GLS activity is upregulated in COVID-19, favoring the catabolism of glutamine." (PMID 37108759, 2023).
Crohn disease (1 paper, 2022). A gastrointestinal disorder characterized by chronic inflammation involving all layers of the intestinal wall, noncaseating granulomas affecting the intestinal wall and regional lymph nodes, and transmural fibrosis. "Clinically low plasma and intracellular Gln concentrations and decreased mucosal glutaminase activity in Crohn’s disease patients indicated that Gln metabolism was impaired therein, from which it was hypothesized that Gln supplementation would improve the clinical manifestations of Crohn’s disease." (PMID 36211442, 2022).
cutaneous melanoma (1 paper, 2025). A primary melanoma arising from atypical melanocytes in the skin. "Glutaminase protein expression differed significantly between OMM and HWDMN, which is in line with previous literature on human cutaneous melanoma compared to normal melanocytes." (PMID 41472129, 2025).
diffuse gastric adenocarcinoma (1 paper, 2026). An adenocarcinoma arising from the stomach. "Background/Objectives: To evaluate the immunohistochemical expression of hexokinase-2 (HK2), glutaminase-1 (GLS1), and fatty acid synthase (FASN) and its prognostic significance in diffuse gastric adenocarcinoma." (PMID 41892863, 2026).
dry eye (1 paper, 2025). "Clinical cases and rodent model showed elevated expression of glutaminase (GLS1), an upstream enzyme in glutamine metabolism, following dry eye injury." (PMID 39837870, 2025).
endolymphatic hydrops (1 paper, 2024). An accumulation of endolymph in the inner ear (labyrinth) leading to buildup of pressure and distortion of intralabyrinthine structures, such as cochlea and semicircular canals. "Additionally, GLS inhibitor CB-839 and inhibitor of the IL-1β receptor Anakinra alleviated the hearing loss and vestibular dysfunction, and reduced the level of glutamate in the endolymphatic hydrop mice." (PMID 39567494, 2024).
fibrosis (1 paper, 2021). the formation of excess fibrous connective tissue in an organ or tissue in a reparative or reactive process. "Glutamine synthetase (GS), as well as other enzymes implicated in glutamine metabolism (glutaminase (GLS), aspartate transaminase (AST) and glutamine dehydrogenase (GDH)), was found to be upregulated during HSC activation both in vitro and in experimental fibrosis." (PMID 34685739, 2021).
fungi infection (1 paper, 2023). "Finally, we detected the glutamine metabolism enzymes GLS, GLS2, and GLUL mRNA expression under fungi infection in murine CD4+ T cells and CD4+ T cells obtained from CD and UC patients." (PMID 37124046, 2023).
HIV-associated neurocognitive disorder (1 paper, 2022). HIV-associated neurocognitive disorder (HAND) remains a common complication of HIV infection in the combination antiretroviral therapy (ART) era. "In pre-clinical studies of EcoHIV Murine Model of HIV-associated neurocognitive disorders (HAND), the inhibition of the glutaminase (GLS) with DON or a DON prodrug JHU083 reversed the impaired cognitive function, indicating the role of the glutaminolysis in HAND26,27." (PMID 35017663, 2022).
Infertility (1 paper, 2023). "The results revealed an increase in GLS and NFE2L2 expression in the endometrium of patients with EMT; however, a decrease in GLS and NFE2L2 expression was observed in the endometrium of patients with infertility." (PMID 38062233, 2023).
inflammatory brain diseases (1 paper, 2017). "Uncovering the important role of glutaminase in inflammation-induced EV release, GLS may provide a potentially pathological mechanism in neuroinflammation, and a possible therapeutic target of inflammatory brain diseases." (PMID 28427419, 2017).
injury (1 paper, 2022). Damage inflicted on the body as the direct or indirect result of an external force, with or without disruption of structural continuity. "However, increasing glutamate production by upregulating glutaminase or decreasing glutamate clearance by downregulating EAAT contributes to the elevated level of extracellular glutamate that characterizes excitotoxic brain injury." (PMID 36362193, 2022).
invasive breast carcinoma (1 paper, 2021). A carcinoma that infiltrates the breast parenchyma. "This study showed a strong trend towards higher GLS protein expression in the high proliferative ER+ tumours in invasive breast cancer and in DCIS." (PMID 34439127, 2021).
lactic acidosis (1 paper, 2023). Metabolic acidosis characterized by the accumulation of lactate in the body. "In summary, either extracellular lactate, acidosis or lactic acidosis enhance glutamine utilisation by inducing glutaminase expression." (PMID 36900208, 2023).
liver cirrhosis (1 paper, 2022). "However, glutamine should be avoided in patients with liver cirrhosis, in which detoxification of ammonia produced from glutamine by glutaminase and glutamate dehydrogenase reactions is impaired." (PMID 36295872, 2022).
lung neoplasm (1 paper, 2016). A benign or malignant, primary or metastatic neoplasm involving the lungs. "Chemotherapy of lung neoplasms induced increase of glutamate content in PBMC and its concentration in serum increased the activity of GDH in PBMC and decreased activity of glutaminase in PBMC." (PMID 28044066, 2016).
malnutrition (1 paper, 2018). Inadequate nutrition resulting from poor diet, malabsorption, or abnormal nutrient distribution. "Prolonged fasting and malnutrition states are associated with reduced GLS activity; on the other hand, GLS activity increases in the postprandial period, after the administration of enteral feeding of branched-chain amino acids and/or l-alanyl-l-glutamine." (PMID 30360490, 2018).
mantle cell lymphoma (1 paper, 2023). Mantle cell lymphoma is a rare form of malignant non-Hodgkin lymphoma affecting B lymphocytes in the lymph nodes in a region called the ``mantle zone''. "GLS the first enzyme in glutaminolysis, is overexpressed in ibrutinib-resistant mantle cell lymphoma (MCL) cells, and that its expression correlates well with elevated glutamine dependency and glutaminolysis." (PMID 36891150, 2023).
metastatic cancer (1 paper, 2021). A carcinoma which has spread from the original site of growth to another anatomic site. "Therefore, we think that the high expression of GLS in CCDR samples is probably due to the increased metabolic activity of metastatic cancer cells." (PMID 35087740, 2021).
metastatic melanoma (1 paper, 2025). A melanoma that has spread from its primary site to another anatomic site. "We showed that GLS overexpression correlated with poor survival in patients with metastatic melanoma." (PMID 40943167, 2025).
mucinous adenocarcinoma (1 paper, 2022). An invasive adenocarcinoma composed of malignant glandular cells which contain intracytoplasmic mucin. "In tumors, we found that compared with adenocarcinoma, PDHA1 and GLS were expressed at low levels in mucinous adenocarcinoma, while CDKN2A was highly expressed." (PMID 36246586, 2022).
non-Hodgkin lymphoma (1 paper, 2020). Distinct from Hodgkin lymphoma both morphologically and biologically, non-Hodgkin lymphoma (NHL) is characterized by the absence of Reed-Sternberg cells, can occur at any age, and usually presents as a localized or generalized lymphadenopathy associated with fever and weight loss. "Similarly, chemical glutaminase inhibitor CB-839 (currently in clinical trials for non-Hodgkin lymphomas) exhibited synergistic or additive effects with NCT-503 for selected dose combinations in four out of five cell lines." (PMID 32138178, 2020).
papilloma (1 paper, 2024). A benign epithelial neoplasm that projects above the surrounding epithelial surface and consists of villous or arborescent outgrowths of fibrovascular stroma. "By the end of the experiment, when the control animals had to be euthanized, there were no papilloma or SCC that lacked both LDHA activity and GLS expression in any of the GLSKOLDHAKO mice." (PMID 39303037, 2024).
prion disease (1 paper, 2024). A transmissible disease that is caused by a protein that is able to induce abnormal folding of normal cellular proteins, leading to characteristic spongiform brain changes, which are associated with neuronal loss without an inflammatory response. "Unlike in prion diseases, we found no significant alterations in glutaminase, glutamate, and glutamine levels in these neurodegenerative disorders." (PMID 39259763, 2024).
retinal degeneration (1 paper, 2025). Degeneration of the retina. "Rod photoreceptor-specific knockout of glutaminase (GLS) displays rapid retinal degeneration and increased markers of cell death." (PMID 40396212, 2025).
type 1 diabetes (1 paper, 2016). "The high levels of glucagon in type 1 diabetes and the low levels of insulin are probably an important cause for the elevated levels of glutaminase in this disease." (PMID 27490892, 2016). "The observation that type 1 diabetes does not affect hepatic L-glutamine transport, however, is a strong indication that glutaminase exerts a key-role in L-glutamine transformation." (PMID 27490892, 2016).
Vestibular schwannoma (1 paper, 2024). A vestibular schwannoma (also known as acoustic neuroma, acoustic neurinoma, or acoustic neurilemoma) is a benign, usually slow-growing tumor that develops from the VIIIth cranial nerve supplying the inner ear. "In this study, we conducted a quantitative proteomic analysis of the VO and ES from patients with MD and vestibular schwannoma (VS), and explored how IL-1β influences glutamate excitotoxicity by increasing the expression of glutaminase (GLS), potentially contributing to the pathogenesis of MD." (PMID 39567494, 2024).
vitiligo (1 paper, 2022). Generalized well circumscribed patches of leukoderma that are generally distributed over symmetric body locations and is due to autoimmune destruction of melanocytes. "In a study of 64 vitiligo patients and 64 controls, a case-control study immunoglobulin an (IG) anti endodermal antibody and IgA anti glutaminase antibody, a diagnostic marker for CD, were tested, and two women with vitiligo were found to be seropositive." (PMID 35321240, 2022).
cancer (654 papers, 2009 to 2026). A tumor composed of atypical neoplastic, often pleomorphic cells that invade other tissues. "To further understand the regulatory mechanisms underlying glutamate dependency in MTAP-deficient cancer cells, we examined the expression of glutaminase 1 (GLS1), the target of CB-839, and key glutamine/glutamate transporters." (PMID 41246302, 2025). "Reprogramming of Gln metabolism is a hallmark of cancer, with dysregulation of glutaminase (GLS) and glutamine synthetase (GS) identified as key events in tumor metabolic rewiring." (PMID 39897038, 2025). "It is important to mention that glutaminase C (GAC), a splice variant of GLS1, is more catalytically active and is the isoform upregulated in a variety of cancers, making it the principal point of therapeutic targeting." (PMID 41450919, 2025). "The conversion process of this amino acid to glutamate via glutaminase (glutaminolysis pathway) was also associated with the aggressiveness of cancer cells." (PMID 39456684, 2024). "Glutamine metabolism and closely linked metabolic networks involving glutamine transporters, glutaminase, aminotransferase, and redox homeostasis are essential for cancer cell survival." (PMID 37009798, 2023). "Inactivation of GLS impairs redox balance, inhibits nucleotide synthesis, causes replication stress, and induces DNA repair in cancer cells." (PMID 37985723, 2023). "Down-regulation of the kidney-type mitochondrial glutaminase encoded by GLS provides another potential new link with mitochondrial/amino-acid metabolisms and neurotransmitter release as well as with cancer and neurological conditions." (PMID 37679383, 2023). "Elevated glutamine metabolism makes cancer cells more susceptible to glutamine deficiency caused by glutaminase inhibitors, which rapidly induces cell death." (PMID 37842240, 2023). "The expression of glutaminase proteins, which regulates the first stage in glutamine metabolism, is associated with the malignancy and pace of cancer progression." (PMID 37946141, 2023). "In drug sensitivity analysis, the expression of CDKN2A, DLAT, PDHA1, and GLS was negatively associated with some or most drugs in the Cancer Therapy Response Portal database, and the expression of DLST positively correlated." (PMID 36588699, 2022). "Glutamine metabolism as well as GLS have been reported to be apparently elevated in diverse cancers and are positively associated with the tumor malignancies." (PMID 35313796, 2022). "The dependence on glutamine has long been recognised as a hallmark of cancer cell metabolism and plays an important role in tumour development, during which GLS is frequently overexpressed in many malignancies and acts as an oncogene to support cancer growth." (PMID 36158220, 2022). "For example, environmental cystine increases glutamine catabolism and renders cancer cells susceptible to a glutaminase inhibitor." (PMID 33401771, 2021). "For example, glutaminase (GLS1), a protein associated with energy metabolism in cancer cells, encodes glutaminase, which catalyzes the hydrolysis of glutamine to glutamate and ammonia and plays a predominant role in the formation of malignant tumors." (PMID 34235071, 2021). "Increased metabolism of Gln, of which the first step is catabolized by glutaminase (GA; EC 3.5.1.2), is a hallmark of cancer." (PMID 32880874, 2020). "Recent efforts have focused on preventing cancer cell proliferation associated with glutamine addiction by targeting glutaminase using the inhibitor BPTES (bis-2-(5-phenylacetamido-1,3,4-thiadiazol-2-yl)ethyl sulfide)." (PMID 29868609, 2018). "Glutaminase and glutamine levels in the cell culture medium correlate with the cancer cell proliferation, whereas glutamate levels are associated with tumour aggressiveness." (PMID 29385093, 2018). "In kidney-type glutaminase, a spliced variant known as glutaminase C (GAC) has been demonstrated to be closely related to cancer initiation and progression." (PMID 28039459, 2017).